FGF23 (fibroblast growth factor 23)
Diseases named in the same sentence as FGF23 in open-access papers (continued):
Sharing a sentence is not in itself a finding about the gene and the disease.
hypophosphatemia (continued). "Hypophosphatemia arising from an intrinsic increase in FGF23 secretion is characterized by reduced phosphate reabsorption, low 1,25D, and high-normal PTH." (PMID 37635983, 2023). "The increase in ALP levels is one of the biochemical hallmarks of this condition, together with hypophosphatemia, and elevated intact FGF23 levels." (PMID 36817604, 2023). "The “Iron and Phosphaturia – ExplorIRON-CKD” study was primarily designed to explore the differential effect of FDI and FCM on fibroblast growth factor 23 (FGF23) and markers relevant to hypophosphatemia and bone metabolism." (PMID 37884522, 2023). "At 12 weeks, Dmp1KO mice showed increased serum FGF23 and parathyroid hormone levels, hypophosphatemia, impaired growth, rickets, and osteomalacia." (PMID 37943605, 2023). "Among these, only sFRP4, like FGF-23, can also suppress the activity of renal 1α-hydroxylase, leading to the occurrence of hypophosphatemia." (PMID 37768354, 2023). "In this case, FGF23 and vitamin D levels were both decreased, suggesting that the pathogenesis of hypophosphatemia was related to reduced intestinal phosphate, calcium, and vitamin D absorption, while the role of FGF23 was not contributory." (PMID 36672478, 2023). "Hypophosphatemia has been attributed to increased circulating levels of fibroblast growth factor-23 (FGF23), the transcription of which is upregulated in an iron-deficient state." (PMID 37908221, 2023). "In prior research, blockade of FGF23 signaling using anti-FGF23 antibody administration for 28 days in 6-day-old Dmp1KO mice fully corrected hypophosphatemia, bone growth, and trabecular bone volume and partially corrected cortical bone mineralization." (PMID 37943605, 2023). "Elevated FGF23 in the kidney suppresses renal tubular phosphate reabsorption and 1α-hydroxylase activity ultimately leading to hypophosphatemia." (PMID 37908221, 2023). "Cutaneous skeletal hypophosphatemia syndrome (CSHS) is a mosaic RASopathy characterized by the association of dysplastic skeletal lesions, congenital skin nevi of epidermal and/or melanocytic origin, and FGF23-mediated hypophosphatemia." (PMID 36943390, 2023). "Tumor induced osteomalacia (TIO) is a rare disease of mineral metabolism, whose clinical picture is dominated by hypophosphatemia usually due to an excess of circulating FGF23 produced by small mesenchymal tumors." (PMID 35381903, 2022). "As conventional medical therapy for FGF23-related hypophosphatemic rickets/osteomalacia, oral Pi salts and active vitamin D analogues have been administered to correct hypophosphatemia and reduced levels of 1,25(OH)2D." (PMID 36246908, 2022). "The combination of hypophosphatemia and FGF23 levels above 30 pg/ml allows for identification of all patients with TIO and genetic hypophosphatemia and excludes all patients with other forms of rickets." (PMID 34910242, 2022). "Hypophosphatemic Hyp mice, which carry a large deletion in the Phex gene, reproduce elevated FGF23 levels and hypophosphatemia and are widely used as a murine model for XLH." (PMID 36246908, 2022). "In PhexL222P mice, an increasing Fgf23 mRNA expression is observed, with a slight but insignificant decrease in the Na-Pi IIa cotransporter mRNA expression level, which could be an indirect cause of hypophosphatemia and so could induce a probable mineralization defect." (PMID 36011266, 2022). "Tumor-induced osteomalacia (TIO) is a paraneoplastic syndrome characterized by severe, rapidly progressing demineralization caused by usually small mesenchymal tumors secreting an excess of FGF23, leading to hypophosphatemia due to phosphate wasting." (PMID 36499221, 2022). "An abnormal response in the renal apparatus to FGF23 action can be observed in acquired nephropathies such as Fanconi syndrome, also characterized by hypophosphatemia, along with tubular dysfunction." (PMID 36499221, 2022).
hypophosphatemia (continued). "Studies have shown that the phenotypes of PHEX knockout mice and Hyp mice overlap, with hypophosphatemia, high FGF23, and osteomalacia phenotypes." (PMID 35654784, 2022). "Excessive concentrations of intact FGF23 lead to renal phosphate wasting, hypophosphatemia, and impaired bone mineralization in patients with normal kidney function." (PMID 35884995, 2022). "XLH patients have elevated serum levels of intact FGF23, resulting in renal Pi wasting, hypophosphatemia, and low to inappropriately normal levels of serum 1,25(OH)2D." (PMID 36246908, 2022). "Biochemically, Hyp mice are characterized by hypophosphatemia, hyperphosphaturia, elevated circulating levels of FGF23, and suppression of the renal production of 1.25(OH)2D." (PMID 35055123, 2022). "In this regard, high PTH and FGF-23 levels are frequent after transplant and contribute to hypophosphatemia." (PMID 35602513, 2022). "The excessive effects of FGF23 result in hypophosphatemic rickets/osteomalacia, which is characterized by renal Pi wasting, hypophosphatemia, inappropriately normal or low levels of serum 1,25(OH)2D." (PMID 36246908, 2022). "Hypophosphatemia and fibroblast growth factor 23 (FGF23) also regulate 1-α-hydroxylase, increasing and decreasing, respectively, the production of calcitriol." (PMID 35745177, 2022). "In patients with FGF23-mediated rickets, 1,25(OH)2D levels are usually low or inappropriately normal in the setting of hypophosphatemia." (PMID 34910242, 2022). "From these results, they proposed a cut-off level of 30 pg/ml to confirm FGF23-mediated hypophosphatemia in children and adults when using the Kainos assay." (PMID 34910242, 2022). "Hypophosphatemia in Hyp mice and patients with XLH is caused by elevated circulating intact FGF23, leading to renal phosphate wasting and suppression of vitamin D hormone production." (PMID 36278488, 2022). "Patients had the expected biochemical findings of FGF23 excess: elevated intact and C‐terminal FGF23, hypophosphatemia, and low or inappropriately normal 1,25D." (PMID 35991529, 2022). "Measurement of serum FGF23 is relevant in any patient with hypophosphatemia and renal phosphate wasting, and in the current review it was never found below the limit of the normal range." (PMID 35857061, 2022). "FGF23 levels were independently associated with plasma phosphate, calcium and eGFR, suggesting that the delayed increase in FGF23 levels observed in INC patients compared to CKD controls was most likely due to concomitant hypophosphatemia and hypocalcemia." (PMID 35011732, 2022). "FGF23 has been reported to be responsible for hypophosphatemia and reduced 1,25-(OH)2D levels in animal models." (PMID 35055123, 2022). "TIO has rarely been described in children but is an important differential diagnosis in adults presenting with bone pain, muscle weakness, fatigue and/or pseudofractures in conjunction with hypophosphatemia and high levels of circulating FGF23." (PMID 34910242, 2022). "- Pre-transplant FGF-23 was the best pre-transplant predictor of persistent hypophosphatemia one year after kidney transplant." (PMID 35602513, 2022). "In this case report, we want to highlight the paramount importance of adequate tumor screening in adult patients with acquired FGF23-dependent hypophosphatemia." (PMID 35145798, 2022). "X-linked hypophosphatemia (XLH) is characterized by increased serum concentrations of fibroblast growth factor 23 (FGF23), hypophosphatemia and insufficient endogenous synthesis of calcitriol." (PMID 36371259, 2022). "In TIO, chronic hypophosphatemia induced by FGF23 leads to a suboptimal supply of phosphate to bone and a subsequently reduced rate of osteoid mineralization, resulting in osteomalacia in adults and rickets in children." (PMID 35693311, 2022). "Hyp mice were characterized by a ~10-fold increase in circulating intact FGF23, hypophosphatemia, increased serum aldosterone, but normal kidney function, relative to wildtype (WT) controls." (PMID 35884995, 2022).
hypophosphatemia (continued). "Both hypophosphatemia and low FGF-23 levels increase Cyp27b1 and inhibit Cyp24a1 expressions and activities." (PMID 35414099, 2022). "Activating mutations of FGFR1 gene are the reason for osteoglophonic dysplasia characterized by high FGF23 levels and hypophosphatemia." (PMID 35084563, 2022). "Genetic and acquired abnormalities in the FGF23 structure and metabolism cause hyper-FGF-23 conditions – manifested by hypophosphatemia, low serum calcitriol, and rickets/osteomalacia." (PMID 36382755, 2022). "Despite their different genetic origins, ARHR1 presentation resembles XLH; pathologically elevated FGF23, reduced 1,25D, and hypophosphatemia contribute to rickets, osteomalacia, and enamel and dentin defects." (PMID 35460154, 2022). "High basal levels of PTH and FGF-23 make post-transplant hypophosphatemia and hypercalcemia a common finding." (PMID 35602513, 2022). "Transgenic mice overexpressing FGF23 exhibit hypophosphatemia, a decrease in circulating 1,25-dihydroxy vitamin D, and an increase in the renal release of phosphate." (PMID 35159314, 2022). "Loss‐of‐function mutations in PHEX lead to mineralization disturbances, including rickets and osteomalacia, due to increased FGF23, low 1,25D, renal phosphate wasting, and hypophosphatemia (Foster, Nociti Jr., & Somerman, 2014)." (PMID 35460154, 2022). "These are generalized inflammation, anemia, hypophosphatemia, hyperparathyroidism, increased fibroblast growth factor 23 (FGF-23) and sleep apnea." (PMID 36475245, 2022). "Rare forms of colon adenocarcinoma are characterized by FGF23 secretion with hypophosphatemia whereas in other forms, plasma FGF23 is increased." (PMID 35084563, 2022). "Acting on renal tubule cells, excess FGF23 decreases phosphate reabsorption and 1,25‐dihydroxy‐vitamin D (1,25D) production, leading to hypophosphatemia, impaired bone mineralization, pain, and fractures." (PMID 35991529, 2022). "These fusion genes are thought to promote hypophosphatemia by enhancing the secretion of FGF23 via a mutant ligand or a mutant receptor in the FGF1-FGFR1 pathway." (PMID 36686800, 2022). "The recent advent of anti-FGF23 antibody therapy in patients with XLH has enabled the effective treatment of hypophosphatemia, and anti-FGF23 therapy significantly improves the bone phenotype in patients with XLH and in Hyp mice." (PMID 36278488, 2022). "Case 1 resumed drinking after discharge, and hypophosphatemia concomitant with high intact FGF23 levels recurred." (PMID 34901334, 2021). "Bone metabolic abnormalities are reported in some cases, such as hypophosphatemia, hypocalcemia, low 25-OH Vitamin D, and elevation of FGF23, PTH and ALP, as well as hyperphosphaturia." (PMID 34360805, 2021). "Our cases were, in some ways, similar to iron infusion-induced FGF23-related hypophosphatemia, which was reported by our laboratory and others approximately a decade ago, indicating that an exogenous factor led to FGF23-related hypophosphatemia." (PMID 34901334, 2021). "In December 2019, burosumab, a human monoclonal anti-FGF23 antibody, was approved in Japan as a therapeutic agent for FGF23-related hypophosphatemia." (PMID 34797338, 2021). "In the future, further investigation is warranted concerning the precise mechanism of the development of FGF23-related hypophosphatemia in limited patients with massive alcohol consumption." (PMID 34901334, 2021). "Based on these studies and the frequent observation of hypophosphatemia among septic patients, we sought to elucidate further the relationship between FGF23 and mineral homeostasis in a clinically relevant murine polymicrobial sepsis model." (PMID 33989306, 2021). "The first group with FGF23‐dependent hypophosphatemia (FDH)—having low TmP/GFR, high cFGF23, normal renal function, and normal or mild PTH elevation—was recruited to assess the effect of elevated cFGF23 upon TmP/GFR in the presence of variable PTH activity." (PMID 33615106, 2021).
hypophosphatemia (continued). "This condition is similar to iron infusion-induced FGF23-related hypophosphatemia in terms of the dysregulation of FGF23 due to exogenous factors." (PMID 34901334, 2021). "It is reasonable to check FGF23 levels in oncologic patients with persistent hypophosphatemia despite adequate supplementation of phosphorus and vitamin D and discontinuation of the drugs known to cause renal phosphate wasting." (PMID 33191899, 2021). "Excessive amounts of fibroblast growth factor 23 (FGF-23) result in hypophosphatemia due to excessive renal phosphate excretion and inappropriately low levels (for the level of phosphate) of 1, 25 di-hydroxy vitamin D (1, 25 [OH]2 D]." (PMID 34290673, 2021). "The alleviation of FGF23-related hypophosphatemia was observed each time he temporarily abstained from drinking for a short period." (PMID 34901334, 2021). "NPT2aKO mice have hypophosphatemia, leading to a physiologic elevation in 1,25D levels and decreased serum FGF23 levels." (PMID 34043707, 2021). "Increased FGF23 activity results in suppressed co-transporters NaPi-2a and NaPi-2c, as well as in decreased 1a hydroxylase expression and hypophosphatemia." (PMID 34068220, 2021). "In the current study, two cases of FGF23-related hypophosphatemia probably induced by chronic alcohol consumption were first introduced." (PMID 34901334, 2021). "Below are examples of two case reports of patients with metastatic breast cancer with severe hypophosphatemia, phosphaturia and elevated serum FGF23, consistent with TIO." (PMID 33191899, 2021). "Chronically elevated concentrations of intact-FGF23 result in phosphaturia and eventually hypophosphatemia, which in turn can lead to serious musculoskeletal complications, including rickets in children and osteomalacia fragility fractures in adults." (PMID 33675347, 2021). "We interpreted his normal serum FGF23 level as inappropriately high for his degree of hypophosphatemia, prompting a search for a suspected TIO locus, which was further considered based on rapid clinical deterioration in a previously healthy patient." (PMID 33615107, 2021). "As the whole phenotype cannot be explained by hypophosphatemia, it appears that FGF23 is essential for other functions besides normal phosphate and vitamin D metabolism." (PMID 34360805, 2021). "In a normal subject, TmP/GFR will be high in the presence of a low serum phosphate level whereas it is low in FGF23 driven hypophosphatemia including TIO." (PMID 33818653, 2021). "Burosumab, a human monoclonal anti-FGF23 antibody, was recently post-marketed in Japan against for FGF23-related hypophosphatemia." (PMID 34797338, 2021). "Biochemical evaluation showed persistent hypophosphatemia with renal phosphate wasting, elevated FGF23, and osteopenia on DXA scan." (PMID 34354845, 2021). "Excess fibroblast growth factor 23 (FGF23), excess PTH, and an increase in extracellular calcium cause hypophosphatemia by lowering the maximum renal phosphate reabsorption threshold (TmP/GFR)." (PMID 33615106, 2021). "Many factors are recognized as contributing to hypophosphatemia, mainly persistent high levels of FGF-23 and PTH and the influence of immunosuppressive drugs." (PMID 33909856, 2021). "Case 1 was a 43-year-old man with progressive worsening multiple pains and muscle weakness who exhibited chronic hypophosphatemia with increased intact FGF23 levels." (PMID 34901334, 2021). "Excess levels of FGF23 lead to chronic hypophosphatemia, which in turn can result in debilitating musculoskeletal deficits." (PMID 33818653, 2021). "During the experiment, PTH levels remained low, and the hypophosphatemia was reproduced by injection of FGF23 in parathyroidectomized rats." (PMID 33191899, 2021). "PHEX is expressed in osteocytes and odontoblasts, and loss-of-function PHEX mutation results in excess circulating fibroblast growth factor 23 (FGF23), leading to hypophosphatemia." (PMID 34141703, 2021).
hypophosphatemia (continued). "Case 2 was a 60-year-old man with recurrent fractures and exacerbation of pain in multiple joints who also exhibited hypophosphatemia with increased intact FGF23 levels." (PMID 34901334, 2021). "In IH1, we suggest that reduced clearance of 1,25-(OH)2D up-regulates FGF23 production and consequently leads to phosphate wasting and hypophosphatemia." (PMID 34721296, 2021). "Two cases of FGF23-related hypophosphatemia probably induced by alcohol were first introduced in this study." (PMID 34901334, 2021). "X-linked hypophosphatemia (XLH) is characterized by elevated serum levels of fibroblast growth factor 23 (FGF23), leading to decreased 1,25 dihydroxyvitamin D3 (1,25D) production and hypophosphatemia." (PMID 34043707, 2021). "The presence of FGF23 level in the normal range should be interpreted as inappropriately elevated and potentially suggestive of TIO, as physiologically FGF23 should be downregulated with hypophosphatemia." (PMID 33615107, 2021). "Two months later (Day 77), laboratory data revealed the recurrence of hypophosphatemia and high intact FGF23 level." (PMID 34901334, 2021). "Rather, a normal C‐terminal or intact FGF23 must be interpreted as inappropriately high in the setting of hypophosphatemia and warrants a search for FGF23‐excess syndromes such as TIO." (PMID 33615107, 2021). "XLH is characterized by elevated serum levels of FGF23 which leads to impaired production of 1,25D and hypophosphatemia." (PMID 34043707, 2021). "We also recently observed normal C-terminal FGF23 levels in a patient who was diagnosed with hypophosphatemia and adrenal CS (unpublished observations)." (PMID 34659120, 2021). "FGF23-related hypophosphatemia in the present cases was strongly suggested to be induced by chronic heavy drinking according to the time course of the serum phosphate and FGF23 levels, which changed in parallel with alcohol consumption." (PMID 34901334, 2021). "This case suggests that hypophosphatemia in the setting of CKD is associated with appropriate physiological suppression of FGF23 production, superseding the tendency for FGF23 to increase in CKD." (PMID 33615106, 2021). "After biochemical discovery of hyperphosphaturic hypophosphatemia at a tertiary referral centre, a FGF23-producing tumor of the mandible was discovered on physical examination, and then surgically removed." (PMID 34149623, 2021). "Laboratory studies indicated elevated serum levels of FGF23, hypophosphatemia, normocalcemia, and low serum levels of 1,25-dihydroxyvitamin D (1,25-vitD) and hyperphosphaturia was noted via urinalysis." (PMID 34203792, 2021). "Contrary to the initial prediction, their hypophosphatemia with high intact FGF23 levels was alleviated a few weeks after their admission to the hospital." (PMID 34901334, 2021). "Since iron deficiency positively correlates with intact FGF23 circulating levels in ADHR patient and results in hypophosphatemia and osteomalacia in mice carrying an AHDR mutation, we induced iron deficiency in control and furin deficient mice." (PMID 34149625, 2021). "In FGF23-mediated hypophosphataemic disorders it improves hypophosphatemia and bone abnormalities in children." (PMID 32130720, 2020). "Conventional therapy of HR includes oral phosphate supplementation and, in forms with FGF23-mediated hypophosphatemia, calcitriol; however, this therapy further stimulates FGF23 excretion, enforcing the renal phosphate wasting." (PMID 33107440, 2020). "Studies in Hyp mice using this novel peptide confirmed that the inhibition of FGF23 signaling in kidney upregulates the expression of the sodium-phosphate cotransporters Npt2a and Npt2c, coupled with the alleviation of the observed hypophosphatemia." (PMID 32982979, 2020). "This relationship is underscored by the fact that oral iron supplementation to patients with ADHR normalized the elevated FGF23 and cured the prevailing hypophosphatemia." (PMID 32476270, 2020).